FAM229A (family with sequence similarity 229 member A)
Tractability: No criterion of Open Targets' tractability assessment is met for any kind of drug.
Gene: Protein-coding gene on chromosome 1 (32,361,270 to 32,364,278, reverse strand). Ensembl gene ENSG00000225828.
Genetic constraint (gnomAD): Loss-of-function variants: 9 observed, 6.38 expected, observed/expected ratio (o/e) 1.41, 90% interval 0.82 to 1.92. That is too few expected variants to judge how well the gene tolerates losing a copy. Missense variants: 196 observed, 126.16 expected, observed/expected ratio (o/e) 1.55, 90% interval 1.38 to 1.75. Synonymous variants: 93 observed, 60.09 expected, observed/expected ratio (o/e) 1.55, 90% interval 1.31 to 1.83.
Homologues: Orthologues: chimpanzee FAM229A (98% identical), macaque FAM229A (94% identical), rat Fam229a (84% identical), mouse Fam229a (83% identical), dog FAM229A (70% identical). Paralogues in human: FAM229B (24% identical).